RNU6-1307P (RNA, U6 small nuclear 1307, pseudogene)
Gene: Small nuclear RNA gene on chromosome 19 (54,263,951 to 54,264,053, reverse strand). Ensembl gene ENSG00000212314.
Homologues: Orthologues: chimpanzee U6 (96% identical), mouse Gm56206 (64% identical), guinea pig U6 (61% identical). Paralogues in human: RNU6-633P (83% identical), RNU6-1145P (83% identical), RNU6-1181P (83% identical), RNU6-371P (83% identical), RNU6-1209P (82% identical), RNU6-1316P (82% identical), RNU6-283P (82% identical), RNU6-1031P (81% identical), RNU6-38P (81% identical), RNU6-393P (81% identical), RNU6-742P (81% identical), RNU6-1083P (80% identical), and 1284 more.